RN7SL166P (RNA, 7SL, cytoplasmic 166, pseudogene)
Gene: Miscellaneous RNA gene on chromosome 13 (19,736,975 to 19,737,254, reverse strand). Ensembl gene ENSG00000275014.
Homologues: Orthologues: chimpanzee Metazoa_SRP (99% identical), macaque Metazoa_SRP (92% identical), macaque Metazoa_SRP (91% identical). Paralogues in human: RN7SL2 (89% identical), RN7SL1 (88% identical), RN7SL3 (86% identical), RN7SL444P (86% identical), RN7SL493P (85% identical), RN7SL47P (84% identical), RN7SL296P (84% identical), RN7SL664P (84% identical), RN7SL301P (84% identical), RN7SL44P (84% identical), RN7SL709P (84% identical), RN7SL597P (83% identical), and 708 more.